GPX4 (glutathione peroxidase 4)
Diseases named in the same sentence as GPX4 in open-access papers (continued):
Sharing a sentence is not in itself a finding about the gene and the disease.
acute kidney injury (continued). "In mice, knockout of GPX4 induced severe acute kidney failure, which could be rescued by Fer-1 treatment." (PMID 33116120, 2020). "Moreover, Lip-1 plays a role downstream of GPX4, which converts reduced GSH into oxidized GSSH: Lip-1 ameliorates acute renal failure in a genetic GPX4 KO mouse model, strongly suggesting an in vivo anti-ferroptosis activity." (PMID 32664576, 2020). "Moreover, liproxstatin-1 attenuated Gpx4 inactivation and acute renal failure in a Gpx4 knockout (KO) mouse model." (PMID 31597407, 2019). "In another study, quercetin was found to increase the levels of SLC7A11 and GPX4 expression and subsequently enhance cell viability, by inhibiting ATF3, thereby reducing the risk of acute kidney injury (AKI)." (PMID 39171207, 2024). "Hence, Friedmann and colleagues demonstrated using GPX4 knockout mice that the absence of GSH-GPX4 axis caused lipid-oxidation-induced acute renal failure and associated death." (PMID 38553658, 2024). "The role of ferroptosis in acute kidney injury (AKI) was first discovered in GPX4-knockout model mice." (PMID 37612411, 2023). "In addition to showing that neuron-specific Gpx4 depletion results in a neurodegenerative phenotype in mice, inducible Gpx4 depletion manifests with a very large amount of renal tubular epithelial cell death that leads to acute renal failure and early death in mice." (PMID 35720308, 2022). "Ferroptosis is essential in the genetic model of inducible whole-body depletion of Gpx4 and in folic acid-induced acute kidney injury (AKI)." (PMID 36516169, 2022). "Finally, the inactivation of GPX4 was found to trigger ferroptosis and acute renal failure in mice." (PMID 35805124, 2022). "In acute kidney injury (AKI) model and tamoxifen-induced systemic GPX4 deletion knockout mice, it is shown that inflammation is associated with ferroptosis of the kidney." (PMID 34413966, 2021). "The expression of GPX4 was reduced, while that of ACSL4 was increased, suggesting the involvement of ferroptosis in AA-induced acute kidney injury." (PMID 40141980, 2025). "Current markers (e.g., GPX4 expression, serum creatinine, and lipid peroxides) lack specificity for ferroptosis-driven CIN, as they are altered in other acute kidney injuries or metabolic disorders." (PMID 41425591, 2025). "Studies on I/R damaged mouse models, GPX4 knockout mice and folate‐induced AKI have shown that ferroptosis inhibitors reduce renal tubular cell death and acute kidney failure." (PMID 40492946, 2025). "A study by Cheng and the team found that Leonurine raises GPX4 and GSH, fixes ultrastructural defects in mitochondria effectively, and greatly lowers ferroptosis in acute kidney injury (AKI), both in vivo and in vitro." (PMID 40534879, 2025). "The deactivation of glutathione peroxidase 4 (GPX4), a key regulator of ferroptosis, leads to acute renal failure by initiating ferroptosis in the tubular cells of the kidneys in mice." (PMID 38465879, 2024). "The present study also showed renal tubular epithelial cell ferroptosis in vivo and in vitro using models of cisplatin-induced acute kidney injury, and we demonstrated that the ROS/HO1/GPX4 axis contributes to ferroptosis." (PMID 36923942, 2023). "In GPX4 knockdown mouse, induction of ferroptosis by depletion of GPX4 increased IRI‐mediated acute renal failure." (PMID 37229485, 2023). "Recent study has shown that Lgmn may mediate renal tubular ferroptosis through the glutathione peroxidase 4 (GPX4) autophagy mechanism, leading to acute kidney injury (AKI)." (PMID 38057699, 2023). "A study using inducible GPX4 knockout mice showed that inactivation of GPX4 resulted in ferroptotic cell death, and that the GSH-GPX4 axis is necessary to prevent lipid oxidation-induced acute renal failure." (PMID 35563704, 2022).
acute kidney injury (continued). "Studies on folic acid-induced acute kidney injury (FA-AKI) revealed that lipid peroxidation, GPX4 depletion, and the application of Fer-1 can protect renal function, and reduce tissue damage and renal tubular cell death caused by folic acid." (PMID 36755884, 2022). "For instance, knockout of glutathione peroxidase 4 (GPX4), a key protein involved in ferroptosis regulation, in mice leads to ferroptosis and acute renal failure." (PMID 33182266, 2020). "In an acute kidney injury model, tFNAs inhibited the cleavage of poly (ADP‐ribose) polymerase, thereby reducing the apoptosis of renal tubular epithelial cells, downregulating GPX4 expression and ROS production and inhibiting ferroptosis." (PMID 39980149, 2025). "In vivo, inducible ablation of GPX4 leads to acute renal failure with characteristics consistent with ferroptotic damage, highlighting the non-redundant role of GPX4 in tissues." (PMID 41155529, 2025). "When GPX4 is absent, acute kidney injury (AKI) arises spontaneously as a result of damage to renal tubules; however, when GPX4 is increased, this damage is lessened." (PMID 38675549, 2024). "Despite this, the deletion of 15-lipoxygenase (15-LOX) fails to prevent glutathione peroxidase 4 (GPX4) knockout-induced ferroptosis in mouse models of acute kidney injury." (PMID 39624080, 2024). "Additionally, andrographolide has been shown to mitigate iron accumulation and lipid peroxidation by upregulating SLC7A11 and GPX4 levels in HK-2 cells via the Nrf2/FSP1 pathway, thus attenuating ferroptosis and alleviating septic acute kidney injury." (PMID 39544947, 2024). "A lack of GPX4 induces ferroptosis, leading to acute renal failure in mice." (PMID 40110131, 2025). "In this paper, the authors used inducible GPX4 (−/−) mice and demonstrated the essential role of the GPX4/glutathione axis in preventing lipid peroxidation; indeed, mice lacking GPX4 undergo acute renal failure and early death: a clear initial implication of ferroptosis in pathological processes." (PMID 38539832, 2024). "In IRI-induced acute kidney injury (AKI), H/R induces the ferroptosis of human proximal tubular epithelial cells (HK-2) through upregulating ACSL4 and COX-2, as well as down-regulating GPX4 and FTH1 in the kidney tissues." (PMID 37048123, 2023). "Additionally, observations in acute kidney injury (AKI) cases have shown that ferroptosis, involving proteins such as Heat Shock Protein 90 (HSP90), can lead to the degradation of GPX4 through the chaperone-mediated autophagy pathway." (PMID 40427462, 2025). "To date, no GPX4 inhibitors have been approved for use in the clinic, and any such inhibitor may carry significant safety liabilities, as it has been shown that mice with a specific deletion of GPX4 in the kidney display acute renal failure." (PMID 36969743, 2022). "Furthermore, in IRI or folate-induced acute kidney injury (AKI) models, HSC70-HSP90-GPX4 interacts with legumain in the kidney to promote chaperone mediated degradation of GPX4, thereby promoting renal tubular cell ferroptosis in AKI." (PMID 35478955, 2022). "In rats with sepsis-induced acute kidney injury (SI-AKI) and human renal tubular epithelial cells (HK-2) with LPS-induced ferroptosis, ginsenoside Rg1 can reduce lipid peroxidation and ferroptosis by reducing iron content, FTL, FTH, and MDA levels while increasing GPX4, FSP1, and GSH levels." (PMID 38213172, 2024).
colorectal cancer (110 papers, 2010 to 2026). A primary or metastatic malignant neoplasm that affects the colon or rectum. "Our study showed that FK866 can cause ferroptosis in colorectal cancer cells via the Stat3/Gpx4 axis, suggesting a potential therapeutic avenue for targeting the Stat3‐Gpx4 pathway." (PMID 40492508, 2025). "Strikingly, the low manganese diet also significantly reduced colorectal cancer formation in both colon epithelial-specific GPX4-deficient and wildtype mice." (PMID 38260380, 2024). "For example, GPX4 expression is reported to be upregulated in hepatocellular carcinoma and colorectal cancer, and high GPX4 expression is associated with poor prognosis in gastric cancer and lung adenocarcinoma." (PMID 36576648, 2023). "Carriers of the GPX4 (rs173041) T allele were associated with an increased risk of developing colorectal cancer in additive and dominant models (p = 0.02 and p = 0.004, respectively)." (PMID 36555402, 2022). "There is also evidence that a higher risk of colorectal cancers is observed in altered SNP (C-T) of the GPX4 gene." (PMID 32679649, 2020). "By analyzing the cBioPortal database, we found that mutations to Ser in USP14 occurred in skin cutaneous melanoma, uterine endometrioid carcinoma, prostate adenocarcinoma, and ovarian cancer, and the mutation of Lys to other amino acids i GPX4 was detected in colorectal cancer." (PMID 38247539, 2024). "In colorectal cancer, Lys mutation to other amino acids was detected in GPX4." (PMID 38247539, 2024). "Ginsenoside, in fact, inhibited GPX4, causing ferroptosis in colorectal cancer cells." (PMID 38213172, 2024). "Interestingly, a polymorphism at the 3' UTR of the glutathione peroxidase GPX4 was recently reported as a risk-modifier for colorectal cancer, the allele associated with lower GPX4 expression being linked to lower cancer risk." (PMID 21118512, 2010). "Acyl-CoA Dehydrogenase Short/Branched Chain (ACADSB) negatively regulates the expression of GPX4 and enhances the accumulation of Fe2+ and lipid peroxidation in colorectal cancer cells, thereby inducing ferroptosis." (PMID 40721409, 2025). "In conclusion, our study identifies DPP7 as a novel regulator of disulfidptosis and immune evasion in colorectal cancer through its interaction with GPX4." (PMID 40576169, 2025). "The analysis of overall survival in colorectal cancer patient samples revealed that patients with high levels of GPX4, PCBP1, and PCBP2 had significantly worse overall survival." (PMID 40619432, 2025). "Conversely, other research suggests that elevated GPX4 expression in colorectal cancer enhances the infiltration of CD4+ and CD8+ T cells and improves the efficacy of PD-1 inhibitors." (PMID 40365295, 2025). "Initially, we transfected AGS gastric cancer cells and SW480 colorectal cancer cells and with GPX4 overexpression plasmid, and Western blot (WB) experiments confirmed the efficiency of overexpression." (PMID 41142608, 2025). "GPX4 expression inhibition can induce ferroptosis in cancer cells and inhibit colorectal cancer proliferation." (PMID 40969276, 2025). "Targeting the NRF2/GPX4 axis sensitizes cancer cells to ferroptosis and improves therapy efficacy, as seen with sorafenib in hepatocellular carcinoma and oxaliplatin in colorectal cancer." (PMID 39935430, 2025). "In particular, it is demonstrated that HPD regulates colorectal cancer ferroptosis by methylating SLC7A11/GPX4 through a moonlighting function." (PMID 41317403, 2025). "In this study, we identified DPP7 as a novel regulator of disulfidptosis and immune evasion in colorectal cancer through its interaction with GPX4." (PMID 40576169, 2025). "In summary, we propose for the first time that FK866 can induce ferroptosis in colorectal cancer cells through the NAD+ metabolism/Stat3/Gpx4 pathway." (PMID 40492508, 2025). "In this study, ferroptosis in colorectal cancer cells is induced by FK866 through the NAD+/STAT3/GPX4 pathway." (PMID 40492508, 2025).
colorectal cancer (continued). "The research reveals that the Nampt inhibitor FK866 can induce ferroptosis in colorectal cancer cells via the NAD+/Stat3/Gpx4 signaling axis." (PMID 40492508, 2025). "A recent study found that targeting AKT significantly induced GPX4-dependent ferroptosis and inhibited the growth of colorectal cancer cells." (PMID 38392340, 2024). "GPX4 expression was shown to decrease in CNC-treated colorectal cancer cells HCT116, which suggests that CNC controls the evolution of colorectal cancer through the ferroptosis pathway." (PMID 39031216, 2024). "For example, in pancreatic cancer cells, high expression of GPX4 was positively correlated with survival, whereas high expression in colorectal cancer cells had a poor survival outcome." (PMID 39850905, 2024). "The role of glutathione peroxidase 4 (GPX4) in ferroptosis and various cancers is well-established; however, its specific contribution to colorectal cancer has been unclear." (PMID 38260380, 2024). "In colorectal cancer, miR-15a-3p promotes ferroptosis by inhibiting GPX4 and increasing the abundance of ROS, Fe2+, and MDA." (PMID 38392340, 2024). "The findings underscore the intricate interactions between GPX4, dietary factors, and their collective influence on colorectal cancer development, providing potential insights for personalized therapeutic strategies." (PMID 38260380, 2024). "In conclusion, the study elucidates the critical role of GPX4 in inhibiting colorectal cancer progression by regulating oxidative stress in a manganese-dependent manner." (PMID 38260380, 2024). "Here, we found that targeting AKT significantly induced GPX4 dependent ferroptosis and suppressed colorectal cancer growth both in vitro and in vivo." (PMID 38102129, 2023). "Resibufogenin inhibits colorectal cancer cell growth and tumorigenesis by triggering ferroptosis and ROS production mediated by GPX4 inactivation." (PMID 37238692, 2023). "In a word, inhibiting AKT activated ferroptosis through FTO/YTHDF2/GPX4 axis to suppress colon cancer progression, which raised FTO/GPX4 as potential biomarkers and targets in colorectal cancer therapy." (PMID 38102129, 2023). "For example, microRNA (miRNA or miR)-15a and miR-15a-3p have been reported to target GPX4 to promote ferroptosis in prostate cancer and colorectal cancer, respectively." (PMID 37488128, 2023). "RSL-3, a pharmacological ferroptosis inducer, triggered colorectal cancer cell death via direct binding and inactivation of GPx4, resulting in the disruption of redox balance." (PMID 36768241, 2023). "Similar to GC cells, targeting the System Xc−/GSH/GPX4 axis is an effective way to inhibit the growth of drug-resistant colorectal cancer (CRC)." (PMID 36105219, 2022). "Our work reveals that the upregulated glutathione peroxidase 4 and ferrous iron in anti-colorectal cancer drug-tolerant persister cells were potential therapeutic targets." (PMID 35719967, 2022). "To confirm the anti-tumor regrowth effect of GPX4 inhibition after the removal of anti-colorectal cancer agents, we used a subcutaneous tumor mouse model." (PMID 35719967, 2022). "Materials and Methods: The expression of GPx4 and GPx8 in 58 specimens of human colorectal cancer tissues and normal tissues was detected by the indirect immunohistochemical method under a light microscope." (PMID 35208621, 2022). "Overall, our findings suggest that GPX4 (rs713041) SNP influences colorectal cancer development and progression with low selenium status playing also a role in different cancers, and that GPX4 (rs713041) SNP influences the risk of stroke and hypertension." (PMID 36555402, 2022). "We suppose ferroptosis was increased after PPy@Fe3O4 treatment, and the metastatic ability of colorectal cancer cells was inhibited by increased GPX4 expression." (PMID 36177184, 2022). "We found that the protein and mRNA levels of GPX4 were higher in cells treated with anti-colorectal cancer agents." (PMID 35719967, 2022).
colorectal cancer (continued). "ROS levels and transferrin expression were elevated in RSL3-treated colorectal cancer cells, while GPX4 expression was reduced." (PMID 36192693, 2022). "High glutathione peroxidase 4 expression correlates with a worse prognosis in colorectal cancer patients." (PMID 35719967, 2022). "Another study showed that miR-15a-3p regulated ferroptosis by targeting glutathione peroxidase GPX4 in colorectal cancer." (PMID 36175889, 2022). "Glutathione peroxidase 4 (GPX4) is an essential regulator of ferroptosis, and an antitumor effect of GPX4 inhibition-induced ferroptosis has been found in a variety of cancers, such as breast, kidney, and colorectal cancers." (PMID 35659304, 2022). "In our study, the presence of GPx4 and GPx8 in healthy colons and colorectal carcinoma was estimated." (PMID 35208621, 2022). "Some studies demonstrated a high nuclear and cytoplasmic GPx4 expression in the tissue of colorectal carcinoma, as well as its high mRNA expression." (PMID 35208621, 2022). "Bioinformatics analysis revealedSFRS9 can bind to GPX4 mRNA which is a key factor in ferroptosis, and its expression in colorectal cancer is significantly positively correlated with GPX4." (PMID 34336668, 2021). "Very recently, it has also been demonstrated that NGAL inhibits ferroptosis in colorectal cancer by decreasing intracellular iron levels and stimulating the expression of glutathione peroxidase 4 (GPX4) in order to prevent membrane lipid peroxidation." (PMID 34830212, 2021). "PRDX5 and GPX4 are candidate targets for cancer chemotherapy, at least for colorectal cancer." (PMID 40831323, 2025). "ACE not only increases Fe2+ levels in colorectal cancer cells by targeting iron chaperones PCBP1/2 and reducing their expression but also disrupts the antioxidant system of colorectal cancer cells by targeting GPX4 and inhibiting its enzymatic activity, leading to its ubiquitin-mediated degradation." (PMID 40619432, 2025). "Furthermore, PCBP1, PCBP2, and GPX4 synergistically promoted ferroptosis in colorectal cancer cells." (PMID 40619432, 2025). "Furthermore, breast and colorectal cancer patients with high expression of GPX4 have poor overall survival rates." (PMID 40259435, 2025). "Additionally, pharmacological inhibition of JNK with SP600125 partially reversed the β-lapachone-induced decrease in SLC7A11 and GPX4 expression levels in colorectal cancer cells." (PMID 40375133, 2025). "BSN suppresses the cell viability of colorectal cancer by inducing GPX4‐regulated ferroptosis." (PMID 39846413, 2025). "In addition to RSL3 inhibiting CRC by suppressing GPX4 and generating ROS, several other small molecules can promote ferroptosis in colorectal cancer cells." (PMID 40721409, 2025). "Conversely, dipeptidyl peptidase 7 (DPP7) promotes colorectal cancer progression by binding glutathione peroxidase 4 (GPX4), stabilising this redox guardian to suppress cytoskeletal disulfide aggregation (e.g., in drebrin, FLNA/B) and evade NK cell cytotoxicity." (PMID 40790550, 2025). "Targeting DPP7 and/or its interaction with GPX4 may represent a novel strategy to enhance the efficacy of immunotherapy in colorectal cancer." (PMID 40576169, 2025). "However, the potential interplay between GPX4 and disulfidptosis, especially within the context of colorectal cancer, still needs to be clarified." (PMID 40576169, 2025). "Targeting GPX4 to induce ferroptosis could inhibit colorectal cancer proliferation and overcome chemoresistance." (PMID 40969276, 2025). "Although ACE significantly inhibited GPX4 and elevated Fe2+ in colorectal cancer cells, thereby inducing ferroptosis, the tumor cytotoxicity of this compound in vivo is unknown." (PMID 40619432, 2025).